PRDX1 (peroxiredoxin 1)
Diseases named in the same sentence as PRDX1 in open-access papers (continued):
Sharing a sentence is not in itself a finding about the gene and the disease.
cancer (continued). "These limitations of Adenanthin impeded the exploration of PRDX1 inhibition in various cancer types." (PMID 36732502, 2023). "Although its role in diseases such as inflammation and cancer has been gradually elucidated as research has deepened, there have been a few studies exploring the expression and mechanism of Prdx1 in OSCC." (PMID 38007535, 2023). "When incorporating adjacent tissues for comparison, it was revealed that the expression of PRDX1 in pan-cancer typically exceeds that in corresponding adjacent tissues." (PMID 37781072, 2023). "The expression of PRDX1 in pan- cancer was detected, and the results showed that the expression of PRDX1 in gastrointestinal cancers was higher than the median level of pan-cancer." (PMID 37781072, 2023). "Initial bioinformatics analysis indicates that PRDX1 expression in gastrointestinal cancers exceeds the median level across pan-cancer." (PMID 37781072, 2023). "Recent research has indicated variability in PRDX1 expression across different cancer types, with high expression being predominantly observed in these four gastrointestinal cancers and, in most instances, unfavorable prognosis." (PMID 37781072, 2023). "The relationship between PRDX1 and cancer, therefore, appears to depend on many factors including tissue specificity." (PMID 37259925, 2023). "We propose that either the high levels of GLUT3 or low levels of PRDX1 or both can be exploited for arsenite-based cancer therapy." (PMID 38067110, 2023). "Prdx1 was reported to enable cancer cells to withstand high ROS stress and acquire resistance to radio- and chemotherapy." (PMID 38007535, 2023). "Prdx1 is a cis-acting ARE-containing target gene of Nrf219 that plays critical role in promoting cancer growth via its diverse activities in metabolizing ROS and serving as a molecular chaperone." (PMID 35027562, 2022). "Abnormal Prdx1 expression has been observed in several human cancers, including breast, colon, esophageal, ovarian, oral, lung, and prostate cancers." (PMID 35027562, 2022). "Most studies on PRDX1 have focused on its antioxidant effect in cancer, and only a few studies have investigated its role in acute neural injury, such as spinal cord injury." (PMID 33833406, 2022). "Prdx1 plays a key role in cellular detoxification, functions as a chaperone, has anti-apoptotic property, is upregulated in cancer and contributes to radioresistance." (PMID 33640700, 2021). "A previous study demonstrated that PRDX1 knockout mice were viable and fertile, but developed severe hemolytic anemia and several malignant cancers, which shortened their life span." (PMID 34353368, 2021). "Another study demonstrated that the treatment of hypoxic cancer cells with β-elemene downregulates the expression of peroxiredoxin 1 (PRX1), a mediator of NF-κB activation." (PMID 34575983, 2021). "Recent studies have found that PRDX1-regulated pathways play an important role in the progression and metastasis of various cancer types." (PMID 32455559, 2020). "Mice knockout for the gene PRDX1 have a shorter lifespan, suffer from hemolytic anemia and, unlike wild-type mice, have a much higher incidence of development of various types of cancer (lymphomas, sarcomas, and carcinomas) over 9 months of age." (PMID 32751232, 2020). "Recently, studies have shown that PRDX1 is up-regulated in several human cancers types, including lung 12, breast 13, hepatocellular 14, colorectal 15, gastric 16, esophagus 17, prostate 18, ovarian 19 and pancreatic cancer." (PMID 31956363, 2020). "Immunohistochemistry results showed that PRDX1 was mainly expressed in the nucleus and cytoplasm of cancer cells." (PMID 31956363, 2020). "LINC00460 and PRDX1 are promising candidate prognostic predictors and potential targets for cancer therapy for HNSCC." (PMID 31429766, 2019). "Previous studies of PRDX1 have been concentrated in the field of cancer, with few studies examining the role of PRDX1 in the field of CNS injury, such as SCI." (PMID 29512938, 2018).
cancer (continued). "Taken together, these genomic studies validate the presence of PRDX1 amplification in human cancers." (PMID 27653015, 2017). "We also summarize the recent advances implicating PRDX1 in cancer development and the importance of targeting ROS‐dependent/redox pathways in anticancer treatment." (PMID 27653015, 2017). "In this paper, we review the structure, effector functions of PRDX1, its role in cancer and the pivotal role of ROS in anticancer treatment." (PMID 27653015, 2017). "Indeed, because higher nuclear Prdx1 expression was significantly associated with better survival in our study, cancers that maintain elevated nuclear Prdx1 levels may have more reduced Prdx1 available in the nucleus to suppress transcription factor DNA binding and activity." (PMID 29190947, 2017). "Disrupting this balance, for example, depleting PRDX1, is expected to augment pro-inflammatory response leading to cancer invasion and metastasis." (PMID 27388124, 2016). "The observations that lung, non-small cell adenocarcinomas have highly enriched levels of TXN and PRDX1, suggest that these two components provide major antioxidant support in combating the oxidative stress accompanying this specific carcinoma in lung." (PMID 26569310, 2015). "Utilizing an independent cohort of patients (cohort 3), we screened for cancer-related signaling proteins altered in PRDX1 positive tumors." (PMID 25011585, 2014). "In agreement with the proteome changes identified by the proteomic analysis, the expression levels of Hsp27, peroxiredoxin 1, and WD 40 were upregulated in the cancer cells with C. cicadae treatment at 500 μg/mL compared with the control cells." (PMID 24872842, 2014). "RPPA screening of cancer signaling proteins showed that ERα protein was upregulated in PRDX1 high tumors." (PMID 25011585, 2014). "Overexpression of peroxiredoxin 1 (Prx1) has been observed in numerous cancers including oral squamous cell carcinoma (OSCC)." (PMID 25162226, 2014). "This screening approach also identified other cancer progression-related proteins differentially regulated by PRDX1 in the ER-positive cohort." (PMID 25011585, 2014). "This is especially relevant in light of PRDX1 being considered a therapeutic target in other cancer types, as well as the recent development of adenanthin as a chemical inhibitor of PRDX1/2." (PMID 25011585, 2014). "Further validation is necessary to address the importance of PRDX1 protein expression in each cancer type." (PMID 25011585, 2014). "PRDX1 is of particular interest due to its known elevated level of gene expression in numerous cancers, including NSCLC." (PMID 23914992, 2013). "The data of paired ESCC with adjacent and normal tissues provided a similar result confirming that Prdx1 was overexpressed in cancer tissues while the paired samples were at a lower level." (PMID 24009050, 2013). "Indirect immunofluorescence assay with cancer cell lines and immunohistochemistry with cancer tissue array slides were also performed to analyze the protein expression profiles of Prdx1 in cancer cells and tissues." (PMID 24009050, 2013). "Among the 7 self-paired cases, the frequency of Prdx1 was significantly higher in the ESCC tissues (7/7) than that in the adjacent carcinoma tissues (3/7) and in the normal tissues (3/7) (P<0.05)." (PMID 24009050, 2013). "PRDX1 is of particular interest due to its known elevated level of gene expression in numerous cancers." (PMID 21980378, 2011). "Another precedent for possible P-DUDES involvement in cancer progression is the human peroxiredoxin 1(PRDX1) that controls neuronal differentiation by thiol-redox-dependent activation of the GDE2 protein." (PMID 20964819, 2010). "The role of peroxirodoxin 1 (PRDX1) in cancer remains controversial." (PMID 40825764, 2025). "It was demonstrated that APE-1/PRDX1 could act as an anti-inflammatory agent avoiding cancer invasion and metastasis." (PMID 38790661, 2024).
cancer (continued). "To further verify whether silencing of PRDX1 induced cancer cell death was also due to ferroptosis, we treated HCT116PRDX1-KD and SW620PRDX1-KD cells with either apoptosis inhibitor (z-VAD) or ferroptosis inhibitor (Fer-1) and then assessed cell viability." (PMID 39430237, 2024). "Cancer patients with stronger Prdx1 expression often suffer from worse outcomes." (PMID 38007535, 2023). "Intriguingly, PRDX1 expression correlates strongly with cancer's onset, progression, and prognosis." (PMID 37781072, 2023). "This research underscores the high expression of PRDX1 in gastrointestinal cancers, its relevance to the diagnosis and prognosis monitoring of these cancers, and its potential to guide clinical treatment for these cancers." (PMID 37781072, 2023). "As such, GLUT3 and PRDX1 are likely to be novel targets for arsenite-based cancer therapy." (PMID 38067110, 2023). "As a vital component of the PRDXs family, the peroxidase activity of PRDX1 plays a key role in maintaining the equilibrium of intracellular reactive oxygen species (ROS), thereby influencing the onset, progression, and prognosis of cancer 78-80." (PMID 37781072, 2023). "Furthermore, the expression of PRDX1 in the majority of cancers is typically higher than in the corresponding adjacent tissues, with this trend being especially pronounced in gastrointestinal cancers." (PMID 37781072, 2023). "Non-immune cells, such as endothelial cells, and cancer-associated fibroblast, were also significantly enriched in the high-PRDX1 group." (PMID 37842089, 2023). "Moreover, existing studies on PRDX1 in these cancers are limited, warranting further research for more conclusive insights." (PMID 37781072, 2023). "PRDX1 is a multifunctional protein involved in cell proliferation, differentiation, and apoptosis that belongs to the peroxidase family and whose function in cancer is not well understood." (PMID 37842089, 2023). "However, emerging studies have revealed that the cancer-promoting actions of Prdx1 can be explained by its physical interaction with different vital regulatory effectors of proliferation and apoptosis and regulation of their activities." (PMID 35027562, 2022). "The elevated expression of PRDX1 was found in various cancers and its downregulation might facilitate a failure of the endogenous antioxidant systems, which protect cancer cells from ROS." (PMID 34771120, 2021). "To further verify the prognostic effect of PRDX1 on malignant tumors, we analyzed the correlation between PRDX1 expression and clinicopathological features that might affect survival outcomes." (PMID 33747258, 2021). "Peroxiredoxin 1 (Prx1) is a key antioxidant protein, upregulated in a variety of malignant tumors." (PMID 34076143, 2021). "It was hypothesized that the downregulation of PRDX1 in cancer cells reduces their ability to deal with the elevated ROS levels, which induces cell death." (PMID 34771120, 2021). "Another outstanding question is how targeting PRDX1 or PRDX1-related antioxidant system would modify the response of cancer cells to transiently high (i.e., at mM ranges for Asc) concentrations achieved by intravenous application of either Asc or Men, and especially both compounds applied together." (PMID 32316111, 2020). "PRDX1 was detected in the cytoplasm of the cancer cells with variable intensity." (PMID 32316111, 2020). "Higher expression of PRDX1 while lower expression of PRDX6 was shown in the colonospheres than their parental cancer cells (HT29), consistent with their expressional differences between normal colon tissues and COAD tumors, indicating their potential functions in driving COAD tumorigenesis." (PMID 32231717, 2020). "Indeed, the previous research from our team and others suggested that the effectiveness Asc or Men against cancer cells can be dramatically increased by genetic or chemical inhibition of peroxiredoxin 1 (PRDX1)." (PMID 32316111, 2020).
cancer (continued). "However, it can be said that PRX1 expression is cell, stage and cancer type dependent, suggesting a potential role of PRDX1 as therapeutic target and useful biomarker." (PMID 33053689, 2020). "Here, we show that the lack of PRDX1 promotes characteristics found in cancer-associated fibroblasts (CAFs)." (PMID 31419957, 2019). "LINC00460 and PRDX1 may serve as biomarkers for accurate prognostic prediction and as potential targets for cancer therapy in HNSCC patients." (PMID 31429766, 2019). "In addition, treatment of a TLR4 ligand (Peroxiredoxin-1) mediates PCa cell growth in a murine cancer model." (PMID 32010622, 2019). "Notably, we have utilised a genome-editing approach to knockout PRDX1/2 in human cancer cells, which in future can become a clinically applicable modality." (PMID 30287919, 2018). "The role for PRDX1 in cancer is complex and multifaceted (reviewed in36)." (PMID 30287919, 2018). "PRDX1 is a potential target for cancer radiotherapy and/or chemotherapy." (PMID 27653015, 2017). "Prdx1 also participates in various age-related diseases and cancers." (PMID 28827763, 2017). "We thus reasoned that redox modulation of cancer cells through peroxiredoxin 1 (PRX1) knockdown could enhance the anticancer activity of vitK3." (PMID 26689287, 2015). "Secretion of PRDX1 by various cell lines has also been reported, and both PRDX1 and 2 are increased in the serum of diabetic patients with peripheral atherosclerotic disease or in the secretome of cancer cells." (PMID 25985305, 2015). "Cancer cell lines with peroxiredoxin 1 (PRX1) gene transiently or stably knocked-down and corresponding controls were exposed to vitK3 as well as a set of anticancer molecules, including vinblastine, taxol, doxorubicin, daunorubicin, actinomycin D and 5-fluorouracil." (PMID 26689287, 2015). "The elevated expression of Prdx1 was also reported in numerous types of cancers by other groups." (PMID 24009050, 2013). "Finally, elimination of peroxiredoxin (PrDX1), a protein involved in antioxidant enzymatic activity, gave rise to mice with severe hematological abnormalities with a very high rate of cancer, although pNENs were in the minority of the cancers observed." (PMID 37568572, 2023). "Similarly, PRDX1 can act as a pro-cancer protein in HCC HepG2 cells." (PMID 36071454, 2022). "Therefore, PRDX1 may be an independent predictor of improved prognosis of ER-positive breast cancer (which differs from other cancers)." (PMID 33747258, 2021). "Prdx-1 are widely expressed hydrogen peroxide scavenger proteins, best known for their role in detoxifying reactive oxygen species, protecting against oxidative stress, DNA damage, and cancer, and have also been suggested to act in cellular signalling and as molecular chaperons." (PMID 33375241, 2020). "Also, our data suggest that inhibiting PRDX1 as cancer therapeutic may inactivate PTEN and activate JNK thereby promoting the CAF phenotype." (PMID 31419957, 2019). "The loss of APE1 interaction with PRDX1 promotes APE1 redox function to activate binding of the transcription factor NF-κB onto the promoter of a target gene, the proinflammatory chemokine IL-8 involved in cancer invasion and metastasis, resulting in its upregulation." (PMID 27388124, 2016). "The expression levels of STMN1 and PRDX1 genes are significantly correlated with MSI status in many cancers, and the strength of the correlation varies depending on cancer type." (PMID 41403955, 2025). "The positive HBXIP/Nrf2 feedback loop promotes the anchorage-independent survival of cancer cells through Nrf2 maintenance of robust ROS levels and HBXIP stabilization of peroxiredoxin 1 (Prdx1) to inhibit JNK activation." (PMID 35027562, 2022). "In this research, we found that PRDX1 staining was significantly higher in CRC tissues than in ANTs and that PRDX1 can inhibit cancer cell apoptosis by decreasing NOXA levels." (PMID 33712558, 2021).
cancer (continued). "For instance, peroxiredoxin 1, an antioxidant enzyme, was observed to inhibit TRAF6 ubiquitin-ligase activity, downregulate autophagy and inhibit cancer cell migration." (PMID 34760883, 2021). "There was variation in expression of SOD2, PRDX1 and GSR that didn’t correlate across the cancer cell lines and fibroblast." (PMID 33669867, 2021). "This is further supported by higher basal p100 Prdx1 levels, high MW p28 Srxn levels, and differential CSA responses in Panc1 and ASPC-1 cancer cells as compared to normal ductal HPDE cells and Kras mutant HPDE-Kras cells." (PMID 29190947, 2017). "Our findings suggest that the interaction of PRDX1 with APE1 represents a novel anti-inflammatory function of PRDX1, whereby the association safeguards APE1 from reducing transcription factors and activating superfluous gene expression, which otherwise could trigger cancer invasion and metastasis." (PMID 27388124, 2016). "To examine the mechanistic basis of Ets2 in ESCC, we determined the effects of Ets2 knockdown on the expression of phosphorylated mTOR (p-mTOR), p70S6K and Prdx1 of ESCC cell in vitro and cancer xenograft mouse model." (PMID 27556183, 2016). "Immunohistochemical study with tissue array slides and western blot analysis with cancer cell lines were also performed to analyze the protein expression profiles of Prdx1 in ESCC tissues and cancer cell lines." (PMID 24009050, 2013). "The result indicated that there was an increased frequency of Prdx1 overexpression in ESCC tissues (100%, 16/16) compared to the adjacent carcinoma tissues (64.3%, 9/14) or normal tissues (50%, 6/12)." (PMID 24009050, 2013). "PRDX1, an antioxidant enzyme, is overexpressed in several cancers and represents a promising target for the development of novel antitumor drugs." (PMID 40771925, 2025). "Intensive ROS scavenging, including peroxiredoxin 1 (PRDX1), SOD2, CAT, GSH-PXs, thioredoxins (TRXs), and GSH, can be upregulated by the activation of TNFα, Nrf2, HIF1α, AMPK, and PGC1α, protecting cancer cells from damage and subsequent cell death." (PMID 38474405, 2024). "For instance, increased levels of PRDX1, PRDX3, and PRDX6 in cancer types like breast cancer, ovarian cancer, and leukemia may lead to resistance to chemotherapy." (PMID 38821929, 2024). "High amounts of PRDX1 and/or PRDX2 and their growth-supporting functions have been documented in several cancer types, suggesting that inhibitors of these enzymes may exert anticancer activity." (PMID 37566013, 2023). "Although PRDX1 has been shown to exert strong antioxidant effects in cancer treatment, its effects in OA have not yet been studied." (PMID 33833406, 2022). "Furthermore, the interaction between PRDX1 and TLR4 in human cancer cells was shown to upregulate HIF-1α, a master regulator of adaptive responses to hypoxia that is highly expressed in NES tissues (Allen and Vázquez-Medina, 2019)." (PMID 34744798, 2021). "Peroxiredoxin-1, a TLR4 ligand, has been shown to interact with TLR4 to promote prostate tumor cell growth through chronic activation of cancer angiogenesis in a murine cancer model." (PMID 29928275, 2018). "Although the function of Prdx1 in the process of carcinogenesis is still not clear, various mechanisms have been recently proposed and verified in certain types of cancer." (PMID 24009050, 2013). "Taken together, these results also indicate that Prdx1 may be a potential therapeutic target for ESCC and other cancers." (PMID 24009050, 2013). "Previous proteomic profiling of urine samples from five individuals with BLCA and five healthy participants demonstrated substantial elevation of PRDX1 levels among cancer patients, suggesting its value as a non-invasive diagnostic indicator for initial screening." (PMID 41019038, 2025). "Furthermore, PRDX1, via Toll-like receptors (TLR4), controls inflammation, immunity, and tissue repair processes, thereby augmenting the cytotoxic activity of NK cells against cancer cells." (PMID 37781072, 2023).